S100A4 (S100 calcium binding protein A4)
Diseases named in the same sentence as S100A4 in open-access papers (continued):
Sharing a sentence is not in itself a finding about the gene and the disease.
breast carcinoma (continued). "In addition, cell-based interactions for biological function of S100A4 have been employed to investigate its effects on the different components of the metastatic process in breast cancer." (PMID 29069865, 2017). "In breast cancer, only S100A4, S100A7, and the heterodimer S100A8-S100A9 are extensively evaluated." (PMID 28051137, 2017). "As a cancer-associated fibroblast-related protein, S100A4 was highly expressed in both the tumor and stromal cells in breast cancer, indicating that S100A4 might be a potential target for breast cancer treatment." (PMID 29069865, 2017). "S100A4 overexpression increased the tumor cell migration capacity and the Ca2+-activated S100A4 was localized to the pseudopodia and the leading edge of migrating breast cancer cells to promote cell migration." (PMID 29069865, 2017). "Furthermore, there is a strong correlation between the expression of S100A4 and poor overall survival as well as the presence of distant metastases in multiple cancer entities, including breast cancer." (PMID 26741489, 2016). "In addition, a previous study has reported high expression of S100A4 in adipocyte-derived fibroblasts, which are a major desmoplastic stroma component in breast cancer." (PMID 26163388, 2015). "Similarly, S100A4 is reported to be overexpressed in metastatic breast cancer cell lines and human tumor tissues." (PMID 26097874, 2015). "The observed increase in S100A4 in our xenograft model is of great interest since it has been shown in several studies how overexpression of this protein is correlated with a poor prognostic outcome in breast cancer patients." (PMID 20723242, 2010). "In addition, MMP7 overexpression has also been reported for a variety of cancers, including those of the oesophagus, stomach, pancreas, lung, colon/rectum and breast cancer, while S100A4 is a mediator of metastasis,[and references therein,41]." (PMID 19578441, 2009). "This suggests S100A4 may play a role in advanced breast cancer especially with lymph node metastasis." (PMID 18771601, 2008). "The difference in the expression of S100A4 protein suggests it may be useful as an independent marker of breast cancer which appears to be down regulated in more advanced stages of breast cancer." (PMID 18771601, 2008). "This study indicates a complex role of S100A4 in breast cancer of different types and stages." (PMID 18771601, 2008). "Our study suggests S100A4 may play a role in breast cancer progression and may prove to be an independent marker of breast cancer which appears to be down regulated in more advanced stages of breast cancer." (PMID 18771601, 2008). "This suggests that critical changes in metastatic potential may be determined early in breast cancer disease using markers such as S100A4." (PMID 15900299, 2005). "In fact, S100A4 was shown to be a significant marker of prognosis even for T1N0M0 breast cancers." (PMID 15900299, 2005). "When S100A4 transgenic mice were mated with neu transgenic mice, known for developing mammary cancer after multiple pregnancies, double-positive offspring that inherited both genes developed mammary tumours with significantly more lung metastases than mice that inherited only the neu oncogene." (PMID 16265347, 2005). "Moreover, elevated expression of S100A4 has been shown to correlate with early patient demise of one group of breast cancer patients, presumably due to metastatic spread of the primary tumour." (PMID 14710237, 2004).
breast carcinoma (continued). "The isolation and culture of tumour cells from both neu and neu/S100A4 transgenic mice increased the efficiency of mammary tumour production from 44 and 68% as seen after 14 months in neu and neu/S100A4 transgenic mice, respectively, to 100% in the nude mice for all of the injected cell lines." (PMID 14710237, 2004). "The results presented in this study are, therefore, the first to demonstrate in a mammary tumour cell system, that cell motility correlates with levels of S100A4 in a statistically significant linear fashion and that, at least in the transfected cell lines, S100A4 is the cause of this change." (PMID 14710237, 2004). "The S100A4 gene, cloned from murine mammary carcinoma cells, has been shown to be specifically expressed in cells with high metastatic capability, but how S100A4 exerts its putative metastasis-promoting effects is largely unknown." (PMID 12439718, 2002). "The main objective of the present study was to study the expression patterns of S100A4 and E-cadherin in a panel of 66 breast cancer biopsies and to investigate whether the expression levels were associated with known tumour variables or patient survival." (PMID 12439718, 2002). "Importantly, S100A4 knockdown diminishes STC1-induced lung metastasis of breast cancer." (PMID 37400459, 2023). "Moreover, there was a lack of correlation between immunohistochemical staining for S100A4 and cell proliferation measured by staining for Ki67 in primary breast carcinomas, despite a strong correlation between staining for S100A4 and patient demise from metastatic breast cancer." (PMID 37509135, 2023). "In addition, some of the modulated proteins found in the present study such as haptoglobin or S100A4 have been related to CMT or human breast cancer previously, which confirms the validity of our study design for CMT evaluation and the use of CMT as a model for breast cancer research." (PMID 32344524, 2020). "Tumor-released S100A4 may stimulate stromal components such as osteoblast-lineage cells to mediate their interplay with osteoclasts, driving the microenvironment favorable for reactivation and growth of breast cancer cells in the bone-metastatic niche." (PMID 31667000, 2019). "Furthermore, we provide in vivo evidence for the role of tumor-derived S100A4 in bone destruction and osteoclast formation by examining the effects of silencing the S100A4 gene and of a S100A4-blocking antibody (Ab) in a mouse xenograft model of breast cancer bone metastasis." (PMID 31667000, 2019). "Hence the involvement of TG2 with S100A4 in mediating the increased migration found in a rat mammary cancer cell line may also be extended to human breast cancer cells." (PMID 23469180, 2013). "However a larger study with more ILC and metastatic cases may clarify the role and function of S100A4 in breast cancer progression." (PMID 18771601, 2008). "In addition to these data for breast cancer, an increase in S100A4 protein expression has been correlated with a worse prognosis for patients with colorectal, gallbladder, bladder, esophageal, non-small-cell lung, gastric, medulloblastoma, pancreatic and hepatocellular cancers." (PMID 15900299, 2005). "We examined the regulatory effect of STC1 on S100A4, and found a STC1–EGFR–ERK–S100A4 signaling axis in lung metastatic breast cancer cells." (PMID 37400459, 2023). "An evaluation of cancer hallmark gene-sets associated with five continuous phenotypes C3, COL11A1, CXCL12, FBLN1, and S100A4 using the aspatial methods including GSEA, LCT, and RF-GSEA on a single cell breast cancer study." (PMID 36998245, 2023). "To date, the relationships between metastasis of breast cancers and the expression of α-SMA and S100A4 by CAFs have been described." (PMID 36768815, 2023). "We found a positive correlation between the expression of S100A4 and STC1 in metastatic lesions of breast cancer patients." (PMID 37400459, 2023).
breast carcinoma (continued). "It has also been reported that S100A4 can physically and functionally interact with Smad3 to increase TGF-β-induced matrix metalloproteinase-9 expression and invasion ability in breast cancer cells." (PMID 36078170, 2022). "Both the expression of S100A4 and the invasion of MDA-MB-231 breast cancer cells were shown to be significantly higher as compared to those for MCF-7 breast cancer cells." (PMID 35546077, 2022). "The Kaplan-Meier survival curve showed that greater expression of S100A4 and CD68 was predictive of reduced relapse-free survival of patients with breast cancer, and of reduced overall survival of patients with ovarian or lung cancer after chemotherapy." (PMID 34145030, 2021). "S100A4 is an agonist of GPCR signaling, including the PLCβ-IP3 pathway, which is known to promote metastasis in breast cancer." (PMID 33806911, 2021). "In saliva, three proteins of the S100A family, namely S100A2, S100A4, and S100A6, were among the most upregulated proteins in bitches with mammary tumors when compared to healthy controls." (PMID 32344524, 2020). "In our current analysis of a public dataset of >1700 breast cancer samples, low RFS in patients with high geminin + HMGB1 + S100A4 (two RAGE ligands)-expressing patients was observed." (PMID 31844158, 2019). "Of all analyzed tissue sections 82.2% expressing CYR61 did express S100A4, respectively, which lead to the conclusion, that CYR61 together with S100A4 would be valuable prognostic marker for breast cancer and breast cancer metastasis." (PMID 31709177, 2019). "We then evaluated the involvement of S100A4 in OSX‐induced cell migration and angiogenesis of breast cancer." (PMID 30450809, 2019). "Immunohistochemistry for S100A4, Fibronectin, RAS, IL-1B, IL-1R1 and γ Catenin was performed on mammary tumours and metastases in human bone implants." (PMID 31783893, 2019). "Further, the synergistic effect of S100A4 by TGF-β-induced extracellular signal-regulated kinase (ERK) signaling indicates the involvement of S100A4 in TGF-β- mediated pro-metastasis and pro-angiogenesis formation of breast cancer." (PMID 29069865, 2017). "High levels of S100A4 and CYR61 were found in biopsy specimens of malignant human breast cancers, whereas in carcinoma, in situ, the expression levels were much lower." (PMID 28824547, 2017). "Among proteins which expression is effected by promoter methylation are S100A4, S100A6, S100A10, S100P which were shown to aberrantly hyper- or hypomethylated in breast cancer, colon, pancreas, prostate, gastric and endometrial cancer, among others." (PMID 26097874, 2015). "The human breast cancer cell line MDA-MB-231 was used to extend our observation for the importance of both TG2 and S100A4 proteins in R37 and KP1 cells to human cancer cells." (PMID 23469180, 2013). "Several cancers, including colon cancer, breast cancer and osteosarcoma, are known to produce S100A4, and particularly, HT29 cells have been described to express a substantial amount of S100A4." (PMID 20515499, 2010). "CTGF is elevated in advanced stages of breast cancer, promotes mesenchymal features in MCF-7 cells when overexpressed, and is an upstream inducer of S100A4, a gene important for its positive effects on cell migration." (PMID 19604397, 2009). "WalBC cells exhibited expression of known markers of basal invasive human breast cancers as well as increased KRT17, KRT 14 and KRT 19, DSP, s100A4, NDRG-1, ANXA1, TK1 and AQP3 gene expression and decreased gene expression of TIMP3, VIM and TAGLN." (PMID 18179684, 2008). "Relaxin decreased cell proliferation and down-regulated cellular S100A4 levels in MDA-MB-231 and T47D breast cancer cells." (PMID 18718015, 2008).
breast carcinoma (continued). "Besides the influence of well-known molecular aberrations in breast cancer such as BRCA1, BRCA2, HER2, and Ras, other genes such as S100A4, TPD52, and CDKs have been identified." (PMID 39355533, 2024). "Furthermore, upon isolating macrophages and Ly6g+ neutrophils from lungs with 4T1 breast cancer metastasis, we found that macrophages expressed higher levels of ApoE, S100A10, and S100A4 than those macrophages isolated from normal mice." (PMID 39695088, 2024). "Overexpression of S100A4 promoted metastasis of non-metastatic human breast cancer cells to the lung and lymph nodes." (PMID 36817446, 2023). "It decreases lung cancer invasion by inhibiting the S100A4/NF-B/MMP9 axis: 350 reduces both the breast cancer cell pulmonary metastases and metastatic potential of lapatinib-resistant breast cancer cells by inhibiting the STAT3-FAK-Src axis and epithelial-mesenchymal transition (EMT), respectively." (PMID 35225948, 2022). "S100A4, also known as fibroblast-specific protein 1 (FSP1), was first identified as a murine fibroblast marker in 1995 and has since been established as a fibroblast biomarker in breast cancer." (PMID 36358721, 2022). "The aim of this study was to investigate the S100A4-mediated mechanisms of auto- and paracrine regulation of: (i) proliferation; and (ii) tumor cell migration of both triple-negative MDA-MB-231 and triple-positive MCF-7 human breast cancer cells." (PMID 35546077, 2022). "In addition, a positive correlation between FGF2 and S100A4 levels was assessed in TNBC samples, suggesting their potential cooperation in this aggressive breast cancer subtype." (PMID 33946884, 2021). "In the present study, we have determined that the expression levels of FGF2 and S100A4 are higher in TNBC with respect to non-TNBC patients when analyzing “The Invasive Breast Cancer Cohort of The Cancer Genome Atlas” (TCGA) dataset." (PMID 33946884, 2021). "S100A4 has been studied in breast cancer models which have shown that over-expression of S100A4 in nonmetastatic mammary tumor cells confers a metastatic phenotype." (PMID 31611628, 2020). "S100A4 was also shown to increase MMP2 levels in MDA‐MB‐231 and MDA‐MB‐468 breast cancer cells." (PMID 30980596, 2019). "The observed change in stress filament abundance is in agreement with findings in MDA-MB-231 breast carcinoma cells, which exhibited an increase in cytoskeletal stress filament formation in the absence of S100A4." (PMID 31652274, 2019). "Whether S100A4 and GRM3 can be utilized as therapeutic targets for bone metastasis from breast cancer is worth further pursuit." (PMID 28615627, 2017). "Non-metastatic human breast cancer cell line MCF-7 acquired a metastatic phenotype after transfection of S100A4 cDNA, whereas a decrease in S100A4 expression in highly metastatic human breast cancer cells clearly suppressed its metastatic potential." (PMID 29069865, 2017). "In addition, S100A4 and cysteine-rich angiogenic inducer 61 (CYR61) promoted breast cancer cell motility, invasion and metastasis through EMT induction, whereas GnRH inhibits such phenotypes." (PMID 29069865, 2017). "Moreover, S100A4 was able to combine with the Rhotekin–RhoA complex to promote membrane ruffling and invasion of epidermal growth factor (EGF)-expressed breast cancer cells." (PMID 29069865, 2017). "S100A4 was expressed at the leading edge of brain metastases in image guided sampling and overexpressed in brain metastatic vs non-brain metastatic primary breast carcinomas." (PMID 27100728, 2016). "The median time until development of BMs after diagnosis of breast cancer was 25.5 months (95% CI: 20.1–30.9) and was no shorter in the S100A4-positive cases (Log rank test P=0.67)." (PMID 27100728, 2016). "In support of this, we show for the first time that S100A4 is overexpressed in brain metastatic over non-metastatic breast cancers." (PMID 27100728, 2016).
breast carcinoma (continued). "When MCF7S1 breast cancer cells were cultured with mammary fibroblasts in 3D culture, the fibroblasts increased expression of the S100A4 metastasis promoting protein, which subsequently increased MMP-2 activity and cytokine secretion within the coculture to promote breast cancer cell invasion." (PMID 25856378, 2015). "Since S100A4 and TG2 are also thought to play an important role in the progression of a number of human cancers including breast cancer, it was important to test our theory in a breast cancer cell system." (PMID 23469180, 2013). "Further analysis of the SELDI-TOF-based tear proteome profiling identified the protein S100A4 to be increased in the tears of breast cancer patients (data not shown)." (PMID 22664934, 2012). "Mechanistic studies demonstrated that overexpression of S100A4 induced metastatic capability in non-metastatic breast cancer cells and stimulated metastasis of benign tumors in transgenic mouse model systems." (PMID 22727333, 2012). "Four (23.5%) cases showed S100A4 expression in the primary breast carcinoma with absent expression in its matched lymph node metastasis." (PMID 18771601, 2008). "The small calcium-binding protein S100A4 was known to enhance cell motility by interacting with non-muscle myosin II and was described to selectively stimulate cell motility in mouse mammary carcinoma cell lines without increasing in vitro invasiveness." (PMID 18718015, 2008). "The main purpose of the study was to find the expression pattern of S100A4 proteins in different types of breast cancer with or without lymph node involvement and to determine its role in breast cancer using tissue microarray." (PMID 18771601, 2008). "It was observed that 12 of 17 (70.5%) paired cases (primary breast cancer with matched lymph node) showed expression of S100A4 in the lymph node metastasis with absent expression in the primary site." (PMID 18771601, 2008). "Despite the association between aggressive tumours and S100A4 expression, the protein level was not a prognostic factor in this panel of breast cancer samples, and further studies are warranted to elucidate the prognostic role of S100A4." (PMID 12439718, 2002). "In mouse models of breast cancer, S100A4 promotes the recruitment of pro-tumor Th2 polarized CD4 T cells to both the primary tumor and metastatic sites to promote disease progression, and antibody blockade of S100A4 reduces CD3+ T cell infiltration in the primary tumor and lung metastasis." (PMID 40078995, 2025). "Therefore, the involvement of S100A4 may convincingly explain the multifunctional regulatory effect of STC1 on breast cancer cells themselves and the tumor microenvironment of breast cancer lung metastases." (PMID 37400459, 2023). "Collectively, these results indicate that recruiting S100A4-expressing inflammatory macrophages plays a vital role in ECM remodeling in the premetastatic niche and may act as a potential therapeutic target for breast cancer lung metastasis." (PMID 35496059, 2022). "Moreover, we identified that OSX could promote the breast cancer cell migration and tumor angiogenesis by increasing S100A4 expression, suggesting that OSX participates in breast cancer malignancy and may serve as a potential target for breast cancer therapy." (PMID 30450809, 2019). "In addition, S100A4 can also combine with several other cytoskeletal proteins such as F-actin, non-muscle tropomyosin, and liprin β1 to promote breast cancer cell metastatic dissemination." (PMID 29069865, 2017). "HOTAIR also silences miR-568 via recruitment of both EZH2 and LSD1 to the miR-568 promoter in breast cancer cells, leading to derepression of the miR-568 target NFAT5, which induces of EMT and invasion in breast cancer via transcriptional activation of calcium binding protein S100A4." (PMID 28430163, 2017). "Furthermore, depletion of S100A4 + stromal cells significantly reduced metastatic potential of orthotopic mammary tumor without affecting primary tumor growth." (PMID 28051137, 2017).